PRDX1 (peroxiredoxin 1)
Diseases named in the same sentence as PRDX1 in open-access papers (continued):
Sharing a sentence is not in itself a finding about the gene and the disease.
osteosarcoma (5 papers, 2012 to 2020). A usually aggressive malignant bone-forming mesenchymal neoplasm, predominantly affecting adolescents and young adults. "Overexpression of PRDX1 was significantly associated with malignancy and poor prognosis of osteosarcoma." (PMID 29492195, 2018). "Elevated PRDX1 levels have also been detected in multiple human osteosarcoma cell lines, including MG-63, SAOS-2 and U2-OS, when compared to osteoblast cells." (PMID 31959767, 2020). "In osteosarcoma cells, PRDX1 promotes cell proliferation and metastasis through regulating Akt/mammalian target of rapamycin (mTOR) signaling pathway." (PMID 31956363, 2020). "Here, we found that knockdown of PRDX1 suppress phosphorylation of Akt/mTOR/S6K in osteosarcoma cells, and overexpression of PRDX1 increase phosphorylation of Akt/mTOR/S6K." (PMID 29492195, 2018). "Our results suggest that aberrant expression of PRDX1 is critical for the metastasis of human osteosarcoma." (PMID 29492195, 2018). "In all, we demonstrated that PRDX1 have the potential of enhancing invasion and metastasis of osteosarcoma cells in vivo." (PMID 29492195, 2018). "Collectively, these results indicate that PRDX1 promotes osteosarcoma invasion and metastasis through enhancing Akt/mTOR pathway." (PMID 29492195, 2018). "EdU Click-assay revealed that the percentage of EdU positive cells were increased in osteosarcoma cells with ectopic PRDX1 expression." (PMID 29492195, 2018). "Comparing to the normal cell line hFOB 1.19, PRDX1 mRNA and protein level was elevated in osteosarcoma cell lines MG-63, U2-OS, and SAOS-2." (PMID 29492195, 2018). "In present study, we found overexpression of PRDX1 was frequently observed in osteosarcoma tissues and human cell lines." (PMID 29492195, 2018). "To define the mechanisms by which PRDX1 promotes invasion and metastasis, we tried to identify potential signal pathway regulated by PRDX1 in osteosarcoma." (PMID 29492195, 2018). "To get the correlation between PRDX1 and osteosarcoma, we screened the PRDX1 expression pattern in 40 pairs of fresh osteosarcoma tissue specimens." (PMID 29492195, 2018). "To determine the roles of PRDX1 in osteosarcoma invasion and metastasis, we established stable cell line of PRDX1 knockdown (U2-OSshPRDX1), PRDX1 overexpression (SAOS-2PRDX1), and scramble control." (PMID 29492195, 2018). "Ectopic expression of PRDX1 promotes osteosarcoma cell migration and metastasis in vitro and in vivo, whereas knockdown of PRDX1 expression suppresses cell metastatic behaviors such as invasion and migration." (PMID 29492195, 2018). "To validating the function of PRDX1 in osteosarcoma metastasis, we rationally chose Saos-2 for the subsequent gain-of-function and U2-OS for loss-of-function studies base on the endogenous expression level of PRDX1." (PMID 29492195, 2018). "Our results show that PRDX1 promotes osteosarcoma cell proliferation, invasion in vitro and tumor formation in vivo, suggesting overexpression of PRDX1 in osteosarcoma related to its development and progression." (PMID 29492195, 2018). "To conclude, we report that PRDX1 is an important regulator of osteosarcoma carcinogenesis, in which PRDX1 promotes osteosarcoma cell proliferation, migration and metastasis by enhancing phosphorylation of Akt/mTOR." (PMID 29492195, 2018). "To test the hypothesis that PRDX1 might promote the metastatic ability of osteosarcoma cells in vivo, we inject the cells with overexpressed or down-regulated PRDX1 into the tail vein of nude mice." (PMID 29492195, 2018). "Taken together, our findings prove the important role of PRDX1 in the molecular etiology of osteosarcoma and suggest that PRDX1 may be a novel prognostic biomarker and therapeutic target for osteosarcoma." (PMID 29492195, 2018). "Collectively, our results indicate that PRDX1 function as an oncogene in osteosarcoma and may serve as a promising therapeutic target." (PMID 29492195, 2018).
osteosarcoma (continued). "Taking together, these data indicates that PRDX1 may contribute to osteosarcoma tumorogenesis and metastasis." (PMID 29492195, 2018). "The biological function of PRDX1 in osteosarcoma is still ambiguous." (PMID 29492195, 2018). "Expression level of PRDX1 is highly correlated with prognosis of osteosarcoma patients." (PMID 29492195, 2018). "Moreover, osteosarcoma patients with high PRDX1 level had poor prognosis than those with low level." (PMID 29492195, 2018). "Notably, expression of PRDX1 significantly increased in lung metastatic tumor, suggesting PRDX1 might play a role in osteosarcoma metastasis." (PMID 29492195, 2018). "Notably, expression level of PRDX1 especially increased in lung lesion of osteosarcoma patients, indicating that PRDX1 may promote lung metastasis." (PMID 29492195, 2018). "Notably, knockdown of PRDX1 inhibit lung metastasis of osteosarcoma cells in vivo." (PMID 29492195, 2018). "In addition, overexpression of PRDX1 promotes lung invasion of tumor cells and downregulation of PRDX1 inhibit lung metastasis in vivo, which further confirmed our in vitro observations that PRDX1 promoted metastasis of osteosarcoma cell." (PMID 29492195, 2018). "Most importantly, log-rank test showed that osteosarcoma patients with high level of PRDX1 had significantly shorter disease free survival (DFS) and overall survival (OS) than those with low level of PRDX1." (PMID 29492195, 2018). "Furthermore, we determined if PRDX1 could promote the invasion of osteosarcoma cells." (PMID 29492195, 2018). "However, the function of PRDX1 in progression and metastasis of osteosarcoma is unknown." (PMID 29492195, 2018). "However, whether PRDX1 participates in metastasis of osteosarcoma remains unknown." (PMID 29492195, 2018). "Expression level of PRDX1 was validated to be the predictors for DFS (P = 0.002 in Univariate-analysis and P = 0.001 in multivariate-analysis) and OS (P = 0.005 in Univariate-analysis and P = 0.004 in multivariate-analysis) in osteosarcoma." (PMID 29492195, 2018). "Here, we demonstrate that PRDX1 overexpressed in osteosarcoma tissues comparing to adjacent non-tumor tissues." (PMID 29492195, 2018). "Remarkably, expression level of PRDX1 was found to be the independent predictors for DFS (P = 0.001 in Univariate-analysis and P = 0.006 in multivariate-analysis) and OS (P = 0.008 in Univariate-analysis and P = 0.007 in multivariate-analysis) in osteosarcoma." (PMID 29492195, 2018).
sarcoma (5 papers, 2013 to 2023). A usually aggressive malignant neoplasm of the soft tissue or bone. "Prdx1 was originally identified as a tumor-suppressor based on the observation that the formation of sarcomas and blood malignancies was increased in Prdx1 gene knockout mice." (PMID 24009050, 2013).
type 2 diabetes (5 papers, 2017 to 2023). "Interestingly, a decrease in Prdx1 has been also associated with the development of impaired metabolism-associated disorders, such as type 2 diabetes and cardiovascular diseases." (PMID 29167640, 2017). "We see that IAPP down-regulates both mitochondrial thioredoxin dependent peroxide reductase and peroxiredoxin 1, thus potentially explaining how oxidative stress is increased in type 2 diabetes." (PMID 30419808, 2018). "Interestingly, some of the down-regulated proteins are known to participate in inflammation (mast cell protease-1, complement C3, T-kininogen 1), adipose tissue metabolism (3-ketoacyl-CoA thiolase B), and oxidative stress (peroxiredoxin-1), or related to steatosis and type 2 diabetes (fetuin-B)." (PMID 31258482, 2019).
breast tumors (4 papers, 2012 to 2024). "As a major consumer of intracellular NAD+, SIRT2 inhibits the peroxidase activity of Peroxiredoxin-1 (Prdx-1) through deacetylation, sensitizing breast tumor cells to increased reactive oxygen species (ROS) levels." (PMID 39513038, 2024). "For another, some studies have shown that PRDX1 is overexpressed in breast tumors compared with normal tissues, predicting poor prognosis." (PMID 34490047, 2021). "PRDX1 protein expression was assessed on a RPPA cohort with clinical data available for 712 primary human breast tumors." (PMID 25011585, 2014). "Of the loci evaluated for LOH in breast tumors, the Arg3 homolog, OTC, displayed LOH in 30% of breast tumors, while the Tsa1 homolog, PRDX1, was lost in 26% of tumors." (PMID 22347400, 2012).
endometrial cancer (4 papers, 2011 to 2025). Primary or metastatic malignant neoplasm involving the endometrium (mucous membrane that lines the endometrial cavity). "PRDX1 was among the oxidative stress proteins that was validated to be significantly elevated in stage I endometrial cancer tissue." (PMID 21980378, 2011). "Upregulation of peroxiredoxin-1 has been reported in endometrial cancer cells." (PMID 35454982, 2022).
ischemia (4 papers, 2016 to 2023). A hypoperfusion of the BLOOD through an organ or tissue caused by a PATHOLOGIC CONSTRICTION or obstruction of its BLOOD VESSELS, or an absence of BLOOD CIRCULATION. "In vitro investigation showed that Prdx1 might play a role in the regulation of proinflammatory cytokine expressions and could be a potential therapeutic target for treating ischemia/reperfusion injury." (PMID 27142532, 2016).
Oral leukoplakia (4 papers, 2019 to 2023). A thickened white patch on the oral mucosa that cannot be rubbed off. "Prdx1 is elevated in oral leukoplakia and dysplastic oral keratinocytes and is crucial for the transformation of precancerous lesions into malignant cancer." (PMID 38007535, 2023). "Furthermore, peroxiredoxin-1 has been shown to inhibit apoptosis via regulation of the apoptosis signal-regulating kinase-1 pathway in oral leukoplakia." (PMID 30917517, 2019).
oral squamous cell carcinoma (4 papers, 2018 to 2025). "Oral squamous cell carcinoma was indicated to have overexpression of PRDX1, PRDX2, and PRDX6." (PMID 40281661, 2025). "Peroxiredoxin 1 (Prdx1), a vital antioxidant enzyme, has been proven to play an important role in the occurrence and development of cancers, but its effects on oral squamous cell carcinoma (OSCC) remain unclear." (PMID 38007535, 2023). "In addition, PRDX1, PRDX2, and PRDX6 have also been reported to be overexpressed in oral squamous cell carcinoma." (PMID 36969053, 2023).
thyroid cancer (4 papers, 2014 to 2022). "PRDX1, PRDX2, and PRDX3 expressions downregulated in papillary and anaplastic thyroid cancers, PRDX4 mRNA expression was moderately increased in anaplastic thyroid cancer tissues, and PRDX6 expression status showed similar levels as well as normal thyroid and thyroid cancers." (PMID 35571253, 2022). "PRDX1, PRDX2, and PRDX3 mRNA synthesis decreased in papillary and anaplastic thyroid cancers, PRDX4 mRNA expression was moderately increased in anaplastic thyroid cancer tissues, and PRDX6 expression status was at similar levels in normal thyroid and thyroid cancers." (PMID 26664298, 2015).
triple-negative breast carcinoma (4 papers, 2017 to 2025). An invasive breast carcinoma which is negative for expression of estrogen receptor (ER), progesterone receptor (PR), and human epidermal growth factor receptor 2 (HER2). "Previously, we used this method to demonstrate that peroxiredoxin 1 (PRDX1) was associated with the nuclear DNA in triple negative breast cancer cells." (PMID 29126443, 2017). "In addition, a recent study concluded that DOX targets the antioxidant enzyme peroxiredoxin 1 (PRDX1) in triple-negative breast cancer cells, causing mitochondrial-oxidative damage and activating the intrinsic apoptosis pathway." (PMID 38397805, 2024). "For instance, recent investigations by Lin’s group have elucidated distinct lncRNA-mediated paradigms: lncRNA LncFASA promotes ferroptosis in triple-negative breast cancer via PRDX1 phase-separation-mediated lipid peroxide accumulation." (PMID 41304936, 2025).
viral infection (4 papers, 2015 to 2025). "PRDX1, an oxidative stress scavenger, plays diverse roles in viral infections, promoting antiviral innate immunity in pseudorabies virus (PRV) via the type I IFN pathway and supporting influenza virus replication by interacting with ribonucleoproteins." (PMID 40725077, 2025). "These two different results suggest that chickens may have different defense mechanisms in response to bacterial and viral infection, and PRDX1 may play a role in chicken resistance to bacterial infection." (PMID 32609751, 2020). "These better physiological conditions persist during viral infection when we observed: upregulation of enzymes responsible for GSH biosynthesis, higher level of PRDX1, maintenance of CAT activity, and a less decrease of GSHPx activity." (PMID 30105026, 2018). "Release of TXN1 was also markedly induced by viral infection while, unlike PRDX1 and PRDX2, little or no TXN1 was released in non-infected cells." (PMID 25985305, 2015).
brain tumors (3 papers, 2019 to 2023). "To gain deeper insight into the expression pattern of PRDX1 and PRDX2 in brain tumors, we first examined the level of each of these isoforms in NT and GBM tissues." (PMID 37566013, 2023).
Burkitt lymphoma (3 papers, 2018 to 2023). A rare form of malignant mature B-cell non-Hodgkin lymphoma. "PRDX1 and PRDX2 are upregulated in Burkitt lymphoma cells, PRDX1 and PRDX3 in primary CLL cells, PRDX1 and TXN1 in B-ALL cells, and TXN1 in the OXPHOS-DLBCL." (PMID 32793211, 2020). "Interestingly, the naturally occurring small-molecular peptidomimetic SK053 targeted PRDX1 and PRDX2, leading to cell cycle arrest and apoptosis in Burkitt lymphoma cells." (PMID 36839749, 2023).
cardiac hypertrophy (3 papers, 2022 to 2023). "It has been reported that the overexpression of Prdx1 in cardiomyocytes of mice prevented transverse aortic constriction (TAC)-induced cardiac hypertrophy and heart failure." (PMID 36720768, 2023). "Myocardial Prdx1 overexpression via AAV9-Prdx1 injection significantly inhibited pressure-overload-induced pathological cardiac remodeling post-TAC, including myocardial hypertrophy, dysfunction, fibrosis, inflammation, and oxidative stress compared with control groups." (PMID 35624741, 2022).
cblC (3 papers, 2018 to 2026). "This type is called epi-cblC and can be due to bi-allelic PRDX1 mutations causing MMACHC epimutation, or it can be digenic with heterozygous PRDX1 and MMACHC pathogenic variants located in trans." (PMID 42002808, 2026). "We identified a patient with an unusually late-onset epi-cblC type due to the compound heterozygous recurrent pathogenic MMACHC:c.271dup, p.(Arg91Lysfs*14) variant and a novel PRDX1:c.599G > A, p.(Ter200=) variant." (PMID 42002808, 2026). "The presence of the PRDX1 mutation and the potential clinical consequences of TESK2 silencing in epi-cblC cases suggest that it should be considered as a distinct entity." (PMID 35440018, 2022). "The RNA-seq data analysis showed that the readthrough transcription of PRDX1 was prolongated through the MMACHC/CCDC163P bidirectional promoter and the TESK2 promoter in fibroblasts of epi-cblC patients." (PMID 35440018, 2022).
cholangiocarcinoma (3 papers, 2013 to 2023). A carcinoma that arises from the intrahepatic biliary tree (intrahepatic cholangiocarcinoma) or from the junction, or adjacent to the junction, of the right and left hepatic ducts (hilar cholangiocarcinoma). "In cholangiocarcinoma, PRDX1 expression also significantly increases, influencing the occurrence and development of cholangiocarcinoma by regulating SNAT1 expression." (PMID 37781072, 2023).
endothelial dysfunction (3 papers, 2013 to 2025). In vascular diseases, endothelial dysfunction is a systemic pathological state of the endothelium (the inner lining of blood vessels) and can be broadly defined as an imbalance between vasodilating and vasoconstricting substances produced by (or acting on) the endothelium. "This trend was reinforced by findings from single-cell sequencing analysis (GSE169471), which demonstrated diminished PRDX1 expression in IPAH capillary endothelial cells compared with healthy tissue, potentially implicating its involvement in endothelial dysfunction, a key aspect of IPAH pathology." (PMID 40646297, 2025).
glioblastoma (3 papers, 2018 to 2023). The most malignant astrocytic tumor (WHO grade IV). "We found that in diffuse astrocytoma, PRDX1 is highly expressed, and in glioblastoma, the expression level of PRDX1 is low." (PMID 30322114, 2018). "Rule 11 involves four functional genes, indicating that high expression of HSPA1B and MARCKS, together with the low expression of RPSAP58 and PRDX1, may indicate that a patient may suffer from glioblastoma." (PMID 30322114, 2018). "Here, we assessed the expression pattern of PRDX1 and PRDX2 in glioblastoma (GBM) and examined the efficacy of their inhibitors in GBM cell lines and patient-derived GBM cells." (PMID 37566013, 2023).
leukemia (3 papers, 2013 to 2025). A malignant (clonal) hematologic disorder, involving hematopoietic stem cells and characterized by the presence of primitive or atypical myeloid or lymphoid cells in the bone marrow and the blood. "PRDX1 expression was markedly higher in these leukemia-like cells at diagnosis or relapse than in normal BM cells." (PMID 40825764, 2025). "Our results also indicate that Prdx1 was not only overexpressed in certain solid tumors, but also in leukemia, suggesting the high relevance of Prdx1 with malignancy." (PMID 24009050, 2013).
lymph node metastasis (3 papers, 2013 to 2023). "A significant correlation was found between the high level of PRDX1 expression and lymph node metastasis and tumor differentiation." (PMID 23914992, 2013). "PRDX1 might be correlated with lymph node metastasis and differentiation, and its elevated expression in TIF may be an adverse biomarker for patients with NSCLC." (PMID 23914992, 2013). "Furthermore, expression of PRDX1 was significantly related to lymph node metastasis and differentiation." (PMID 23914992, 2013).
multiple myeloma (3 papers, 2016 to 2020). "PRDX1 is expressed in germinal center B cells and plasma cells and in germinal center derived B cell lymphomas and multiple myeloma." (PMID 26752561, 2016).
Obesity (3 papers, 2015 to 2022). Accumulation of substantial excess body fat. "Our study showed for the first time a high circulating Prdx1 concentration in NAFLD patients with obesity and that its level decreased one month after LSG." (PMID 36619535, 2022). "Preoperative Prdx1 (ng/mL) was significantly higher in NAFLD patients with obesity than in normal controls (25.51 [18.51-32.83] vs. 12.38 [8.370-15.71], p<0.001)." (PMID 36619535, 2022). "The preoperative circulating Prdx1 levels of NAFLD patients with obesity were significantly reduced after LSG (25.32 [18.99-30.88] vs. 23.34 [15.86-26.42], p=0.001)." (PMID 36619535, 2022). "Our study showed that treatment with pre-Q upregulated expression of PRDX1 in cells and obesity triggered its upregulation in tumor bearing animals." (PMID 35816618, 2022). "According to our findings, baseline TyG was an independent predictor of HSI remission at three months after LSG in NAFLD patients with obesity, and it is the first time that circulating Prdx1 is proposed as a promising biomarker to assess postoperative improvement of obesity and NAFLD." (PMID 36619535, 2022). "Prdx1 was related to obesity and hepatic steatosis based on correlation analysis." (PMID 36619535, 2022). "The baseline Prdx1 (OR: 0.887, 95% CI: 0.816-0.963, p=0.004), preoperative TyG (OR: 8.207, 95% CI: 1.903-35.394, p=0.005) and HSI (OR: 0.861, 95% CI: 0.765-0.969, p=0.013) levels were independently associated with NAFLD-I at three months after LSG in NAFLD patients with obesity." (PMID 36619535, 2022). "Additionally, Prdx1 was positively correlated with hepatic steatosis, obesity, ALT and AST." (PMID 36619535, 2022). "In keeping with our hypothesis of inflammation-induced damage to PVAT function in obesity, there are lower levels of SOD1, peroxiredoxin-1 and adiponectin in obese human PVAT." (PMID 26910225, 2015).